MIR487A (microRNA 487a)
Synonyms: hsa-mir-487; hsa-mir-487a; MIRN487; MIRN487A; mir-487a
Gene: MicroRNA gene on chromosome 14 (101,052,446 to 101,052,525, forward strand). Ensembl gene ENSG00000207742.
Gene Ontology:
Biological process: miRNA-mediated post-transcriptional gene silencing
Cellular component: RISC complex
Homologues: Orthologues: chimpanzee ptr-mir-487a (99% identical), dog MIR487A (98% identical). Paralogues in human: MIR539 (78% identical), MIR494 (76% identical), MIR382 (75% identical), MIR154 (74% identical), MIR487B (74% identical), MIR410 (69% identical), MIR1185-1 (68% identical), MIR1185-2 (65% identical), MIR323A (65% identical), MIR496 (65% identical), MIR323B (61% identical), MIR381 (61% identical), and 4 more.
Diseases named in the same sentence as MIR487A in open-access papers:
MIR487A is named in the same sentence as 2 diseases in open-access papers, as found by Europe PMC text mining. Sharing a sentence is not in itself a finding about the gene and the disease. The quoted sentences say what the papers report.
cancer (1 paper, 2023). A tumor composed of atypical neoplastic, often pleomorphic cells that invade other tissues. "MIR487A (chr14:101518782–101518862), which promotes tumor growth and metastasis in other cancers, was hypomethylated in four patients." (PMID 37742993, 2023).
MIR487A also shares sentences with these, for which no sentence is quoted: tumor (1 paper).